EGF (epidermal growth factor)
Diseases named in the same sentence as EGF in open-access papers (continued):
Sharing a sentence is not in itself a finding about the gene and the disease.
breast tumor (43 papers, 1989 to 2025). "These immune cell association patterns suggest that both CCL18 and EGF are engaged in complex immune regulatory processes within breast tumors." (PMID 40692603, 2025). "In breast tumor microenvironments, gradients of EGF secreted by tumor associated macrophages (TAMs) act as chemo-attractants leading to cancer cell polarization toward EGF." (PMID 24093776, 2013). "EGF released by the stromal microenvironment surrounding the breast tumor activates signaling cascades that overlap with PRLr signaling cascades upon activation with PRL secreted by breast tumor cells." (PMID 40160874, 2025). "The analysis revealed significantly reduced promoter methylation levels for both CCL18 and EGF in primary breast tumor samples relative to normal breast tissues (normal n = 97; tumor n = 793; p < 0.05)." (PMID 40692603, 2025). "In vivo studies revealed that PTPN5 inhibits the growth of breast tumors by blocking the epidermal growth factor (EGF)-induced MAPK signaling pathway." (PMID 35681895, 2022). "In our published studies we demonstrated that the exposure of Luminal-A breast tumor cells to combined “TME Stimulation” by estrogen+TNFα+EGF for three days in culture had driven a high in vivo metastatic phenotype in Luminal-A breast tumor cells." (PMID 27835603, 2016). "In view of the role of EGF in the MDA-MB-231 breast tumor model, we first evaluated the ability of either peptide to bind to this growth factor." (PMID 25373734, 2014). "TAMs are localized at the invasive edges of breast tumors and have been known to promote cancer cell invasion by secreting epidermal growth factor (EGF;)." (PMID 24675570, 2014). "This “combined stimulation” by TNFα + Estrogen + EGF provides a more relevant representation of the multifaceted nature of the tumor microenvironment in luminal breast tumors than the reductionist approach of testing the activity of each element alone." (PMID 24369447, 2013). "In Boyden chamber assays, human breast tumor cells have been shown to chemotact up gradients of both EGF and SDF-1α." (PMID 23869217, 2013). "TGFα, whose overexpression drives the breast tumors in the mouse model studied here, is closely related to EGF and an activating ligand for the proto-oncogene Her2, also called Neu or ErbB-2, a member of the EGFR family." (PMID 24279986, 2013). "Overall, our findings indicate that TNFα induces many metastasis-related functions in luminal breast tumor cells and that its activities are largely amplified by cooperativity with estrogen and EGF." (PMID 24369447, 2013). "TNFα, estrogen, and EGF were each shown to have the potential to promote metastasis-related properties in breast tumor cells; however, different research systems were used for the study of each of these factors." (PMID 24369447, 2013). "We have previously reported that TLN-4601 inhibits cell proliferation and Ras-ERK signaling in EGF-stimulated human breast tumor cells with wild type K-Ras (MCF7)." (PMID 21044336, 2010). "We have previously illustrated that TLN-4601 inhibits the EGF-induced Ras-ERK MAPK signaling pathway in human breast tumor (MCF7) cells." (PMID 21044336, 2010). "Aberrant signaling by ErbB-2 (HER 2, Neu), a member of the human Epidermal Growth Factor (EGF) receptor family, is associated with an aggressive clinical behaviour of carcinomas, particularly breast tumors." (PMID 17010186, 2006). "Yet, failure to demonstrate experimental evidence of novel mechanisms for EGF-triggered breast tumor proliferation might be considered a limitation of the present study." (PMID 31532771, 2019). "Indeed, in this study we demonstrate that the combined TME Stimulation by estrogen+TNFα+EGF has enriched Luminal-A breast tumor cells not only for the CD44+/β1+ sub-population, but also for the CD44+/CD24low/− sub-population." (PMID 27835603, 2016). "PBX1 regulates a subset of EGF-ERα genes highly expressed in aggressive breast tumours." (PMID 26215677, 2015).
breast tumor (continued). "Therefore, Brk stimulates the proliferation of breast tumor cells and mediates epidermal growth factor (EGF)-induced mitogenic and migratory effects." (PMID 24736807, 2014). "In view of the multi-factorial nature of the tumor microenvironment, in this study we determined the combined impact of the three arms—inflammatory (TNFα) + hormonal (estrogen) + growth-supporting (EGF)—on malignancy-promoting characteristics and functions of luminal breast tumor cells." (PMID 24369447, 2013). "Other studies denoted that about 70% of breast tumors express the ligand EGF." (PMID 24369447, 2013). "Our findings have shown that as a result of the combined stimulation by TNFα + Estrogen + EGF, luminal breast tumor cells have gained an extensive spreading phenotype in which Src activation has given rise to tumor cell spreading and to localization of FAK and paxillin in tumor cell protrusions." (PMID 24369447, 2013). "The NogoB/NgBR signaling axis is suggested to modulate the EGF/Ras/Raf/ERK and PI3K/Akt signaling pathways and increases the expression of an anti-apoptotic protein called survivin, both of which are shown to be associated with the development and survival of breast tumor cells." (PMID 37511924, 2023). "A recent study found that LAD1 is associated with malignant and aggressive human breast tumors, and the authors have proved through in vitro studies, animal models, and clinical data that the widespread expression of LAD1 acts as a substrate for the downstream phosphorylation of the EGF pathway." (PMID 36770773, 2023). "Consequently, we considered their anti-tumoral potential in EGF-dependent MDA-MB-231 breast tumors." (PMID 25373734, 2014). "Therefore, elucidation of the mechanism of EGF-dependant activation of ER could be important in the development of new therapeutic targets for overcoming the resistance of breast tumor cells to hormone-therapy." (PMID 18509470, 2008). "In 1988, amphiregulin (AR), an epidermal growth factor (EGF)-like growth factor, was found to bind only to the EGF receptor (EGFR) and regulate the growth of MCF-7 breast tumor cells in a serum-free medium." (PMID 38957445, 2024). "For that purpose, we transfected siRNA sequences against vimentin (Vim Si1 and Vim Si2) in well-known EMT+ MDA-MB-231 human breast tumor cells and in human cell systems previously reported to be inducible for EMT by EGF (MDA-MB-468, PMC42-LA) or TGF-β1 (Α549)." (PMID 32152404, 2020). "We found that signal peptide-CUB (complement protein C1r/C1s, Uegf, and Bmp1)-EGF (epidermal growth factor) domain-containing protein 2 (SCUBE2), a tumor suppressor gene, was hypermethylated in breast tumors." (PMID 31404982, 2019). "Above, we have shown that the combined stimulation by TNFα + Estrogen + EGF has strongly induced spreading and EMT properties in luminal breast tumor cells." (PMID 24369447, 2013). "In our study, we have compared side by side the ability of TNFα, estrogen, and/or EGF to affect spreading and EMT properties, using the MCF-7 luminal breast tumor cells." (PMID 24369447, 2013). "Using the joint powers of the TNFα + Estrogen + EGF stimulation, we found that MCF-7 luminal breast tumor cells have acquired very high metastasis-related functions." (PMID 24369447, 2013). "Urine samples from patients with breast tumours and from age matched controls gave TGF-alpha amounts ranging from 0 to 61.5 ng 24 h-1 compared to urogastrone epidermal growth factor figures of 3.0-26.2 micrograms 24 h-1." (PMID 2785399, 1989). "Given the relatively large number of reports on the effect of EGF on breast tumor cell proliferation, this study did not attempt to probe deeper into the detailed signaling pathways that mediate this response." (PMID 31532771, 2019).
breast tumor (continued). "The phosphorylation of these substrate candidates induced by EGF stimulation (a known PTK6 stimulus) remained unchanged following treatment with PTK6 inhibitors in breast tumor cells MDA-MB-231 and HCC1954 (data not shown), casting a doubt if they are physiological PTK6 substrates in tumor cells." (PMID 29879184, 2018). "We used CXCL12 (also known as SDF-1α) and epidermal growth factor (EGF), two well-known extracellular signaling molecules that co-exist in the tumor microenvironment (e.g. lymph nodes or intravasation sites), and a malignant breast tumor cell line, MDA-MB-231, embedded in type I collagen." (PMID 23869217, 2013). "In these cells, EGF stimulation has induced the expression of CXCL8, indicating that activation of RTKs is a relevant pathway for induction of CXCL8, which may account for Ras hyper-activation in breast tumor cells that do not carry mutated Ras." (PMID 24598028, 2014).
head and neck cancer (35 papers, 1995 to 2025). A primary or metastatic malignant neoplasm affecting the head and neck. "Specific combinations of keywords were used: (“salivary cytokines” OR “salivary interleukin 6” OR “salivary interleukin 8” OR “salivary epidermal growth factor”) AND (“head and neck cancer”) AND (“radiotherapy”)." (PMID 41220465, 2025). "Endothelial cell-secreted epidermal growth factor induces epithelial-to-mesenchymal transition in head and neck cancer cells." (PMID 39027882, 2024). "Other secretory factors that can increase CXCL1 expression in head and neck cancer cells are interleukin-1α (IL-1α) and epidermal growth factor (EGF), as suggested by experiments in mouse models." (PMID 37408240, 2023). "In previous studies, VEGF and EGF have been shown to correlate with worse prognosis in both head and neck cancer and esophageal cancer." (PMID 31750257, 2019). "In a previous study by the same author, with 18 head and neck carcinoma patients, EGF in saliva was also shown to decrease during RT due to reduced concentration and reduced saliva volume as radiation treatment progressed." (PMID 31700580, 2019). "A recent study on head and neck cancer also highlighted a role for endothelial cells in regulating CSCs, in which endothelial cells were shown to secrete epidermal growth factor (EGF) to induce EMT and promote cancer stemness." (PMID 28337221, 2017). "In head and neck cancer, it was shown that inhibiting both mTORC1 and mTORC1 increased sensitivity to epidermal growth factor inhibitors; thus, we believe that OSI-027 should be used with other chemotherapy agents, such as GEM, to increase their efficacy." (PMID 26213847, 2015). "Furthermore, EpEX, as a ligand of EGFR, is capable of activating the EGF/EGFR signaling pathway in head and neck cancer cells." (PMID 38791091, 2024). "This review provides evidence that when Akt, a signalling protein, is activated by different growth factors such as epidermal growth factor, transforming growth factor α/β, vascular endothelial growth factor and nerve growth factor, head and neck cancer cell spreading is stimulated." (PMID 35681586, 2022). "In addition, patients with oral mucositis induced by radiation therapy for head and neck carcinoma were also found to have markedly low salivary EGF levels." (PMID 29657585, 2018). "Flow cytometric analysis showed that a small population of SCC-1 cells (∼7-8%) was positive for CD44, a commonly used cell surface marker for head and neck cancer stem-like cells, while EGF stimulation upregulated CD44 expression and significantly enriched the fraction of CD44+/CD24low/− cells." (PMID 27926487, 2017). "Meanwhile, EGF stimulation endows head and neck cancer cells with stem-like cell properties." (PMID 27926487, 2017). "Specific combinations of keywords were used, including salivary cytokines, interleukin-6 (IL-6), interleukin-8 (IL-8), epidermal growth factor (EGF), head and neck cancer, and radiotherapy." (PMID 41220465, 2025). "A collaboration of EGF and EpEX in epithelial–mesenchymal transition (EMT) induction is observed in endometrial cancer cells; however, the opposite result occurs in head and neck cancer cells." (PMID 38791091, 2024). "The cellular components synthesise growth factors such as EGF, TGFα and β, VEGF, and NGF, which have been shown to initiate paracrine signalling in head and neck cancer cells by binding to cell surface receptors." (PMID 35681586, 2022). "Several lines of evidence have demonstrated that EGF can induce EMT in various types of cancer cells, including breast cancer, prostate cancer, cervical cancer, and head and neck cancer." (PMID 27926487, 2017). "EGF stimulated activation of ERK1/2 and Akt by enhancing kinase phosphorylation in head and neck cancer cells." (PMID 25797258, 2015).
head and neck cancer (continued). "The EGF-stimulated phosphorylation of Axl also occurred in a second GBM cell line but was not unique to cells of this cancer type, as it was also observed in cell lines derived from other solid cancers including breast and head and neck cancer." (PMID 27775700, 2016). "Interestingly, we found that EGF significantly induced PTX3 gene expression and protein production in time-dependent manners in head and neck cancer cell lines, but a tiny induction was observed in HeLa cells." (PMID 25797258, 2015). "Therefore, we evaluated the wound healing effect of human recombinant epidermal growth factor (rhEGF) in head and neck cancer and lymphoma patients with irradiation (with or without combined chemotherapy-induced oral mucositis)." (PMID 19456848, 2009). "Serum levels of the soluble epidermal growth factor receptor (sEGFR) and its ligands epidermal growth factor (EGF), transforming growth factor-α (TGF-α) and amphiregulin (AR) were measured in healthy donors and patients with non-small cell lung cancer (NSCLC) and head and neck carcinoma (HNC)." (PMID 17453000, 2007). "Revisiting this role in the context of head and neck carcinoma cells, UM-SCC47 cells were observed to invade through LN332-coated filters in response to EGF with little to no invasion observed under serum-free conditions if EGF is not added." (PMID 31235839, 2019).
liver cancer (34 papers, 2011 to 2025). An epithelial or non-epithelial malignant neoplasm that arises from the liver. "AKR1B10 is upregulated by EGF and insulin through AP-1 signaling and is associated with the development of liver cancer." (PMID 39001490, 2024). "The EGF receptor (EGFR) plays a link between inflammation and liver cancer, and EGF gene polymorphisms have been reported to be associated with HCC risk." (PMID 22235351, 2012). "In our previous work, we proved that cytokines such as transforming growth factor-beta 1 (TGF-β1), tumour necrosis factor-alpha (TNF-α) and epidermal growth factor (EGF) induce the EMT of liver cancer cells in vitro." (PMID 38067256, 2023). "The Ge Feng team found that CDR1as affects the expression of the epidermal growth factor by “adsorbing” miRNA-7, which ultimately affects the cell proliferation of liver cancer cells." (PMID 35682879, 2022). "We further confirmed that EGF signaling is critical for the proliferation of liver cancer cells by EGFR inhibitor SC0186." (PMID 32298294, 2020). "In a liver cancer pathway gene expression profile analysis of HepG2 cells transfected with C/EBPα-saRNA, EGF, EGFR, ADAM17 and β-catenin involved in EMT were down-regulated." (PMID 27050434, 2016). "Epidermal growth factor (EGF)-surface modified SLNs were developed to deliver doxorubicin in the liver cancer model." (PMID 27589733, 2016). "Mapping of EGF induced liver cancer in a transgenic mouse model identified n = 96 (p < 0.05) significantly regulated proteins of which n = 54 were tumour-specific." (PMID 25872475, 2015). "We compared our previously published transcriptomic data of EGF induced liver cancers with the proteomic data obtained in the present study." (PMID 25872475, 2015). "Note, a regulatory loop was proposed whereby EGF induces transcriptional activation of HDAC2 by CK2Α/AKT activation in liver cancer cells." (PMID 25872475, 2015). "The histopathology and oncogenomics of EGF induced liver cancers was previously reported and an important finding of the study was the 100% incidence of malignant tumour formation in less than one year after birth." (PMID 25872475, 2015). "In the present study disease proteomics was performed to further investigate the role of EGF in liver cancer." (PMID 25872475, 2015). "We previously reported the regulation of P2 promoter driven HNF4α isoforms in hepatocarcinogenesis and an identification of novel disease candidate genes found to be regulated in an EGF-induced mouse liver cancer model and human HCC." (PMID 25901575, 2015). "Reconstruction of signalling cascades upstream of these TFs allowed us to suggest the downstream targets of EGF signalling in these two types of cellular states, i.e. transgenicity and liver cancer." (PMID 21464922, 2011). "Whether RNF12 could activate EGF/EGFR signalling by interacting with EGFR to promote the progression of liver cancer was therefore a pertinent question." (PMID 37132043, 2023). "Indeed, a recent study found that inhibition of NatB significantly decreased EGF-induced ERK activation in human liver cancer cells." (PMID 32559195, 2020). "Proinflammatory stimuli activated by EGFR promote the release of EGFR ligands, such as heparin-binding-EGF (HB-EGF), from liver cancer cells and endothelial cells, which stimulate the proliferation of initiated hepatocytes, and further potentiate their aggressive behavior." (PMID 30627539, 2018). "Clinical significance of the identified proteins could be demonstrated and a total of 37 so far unkown proteins could now be related to EGF induced liver cancer, several of which are likely candidates for the development of molecularly targeted therapies." (PMID 25872475, 2015). "In addition, the development and progression of liver cancer and liver metastases is a multifactorial process, linked to alterations in some prominent cellular signaling pathways, including dysregulation of HGF, EGF, and IGF-1." (PMID 34572344, 2021).